PREX2 (phosphatidylinositol-3,4,5-trisphosphate dependent Rac exchange factor 2)
Diseases named in the same sentence as PREX2 in open-access papers (continued):
Sharing a sentence is not in itself a finding about the gene and the disease.
tumor (continued). "The upregulation of PREX2 and its mRNA increasing expression led to the AKT activation by PTEN phosphorylation and increases tumor proliferation." (PMID 32850962, 2020). "In total, recurrent (>3) MEI were observed in 329 protein-coding genes of which 28 genes are annotated in the Cancer Gene Consensus with either oncogenic (ALK1, ERBB4, TSHR, PREX2, CTNNA2, CTNND2) or tumour suppression roles (EBF1, LRP1B, PTPRD, GPC5, ROBO2, PTPRT)." (PMID 35301290, 2022). "PREX2 has been identified as a PTEN inhibitor and thus plays a role in tumor proliferation." (PMID 30796242, 2019). "Similarly, genetic targeting of PREX2 had no impact upon tumor take or growth kinetics under basal conditions and provided no additive benefit to the cobimetinib/dabrafenib doublet." (PMID 39636745, 2025). "Interestingly, the protein levels of PREX2 in tumor tissues were higher than those in corresponding normal tissues, which may suggest a post-translational modification." (PMID 30796242, 2019).
cancer (29 papers, 2016 to 2025). A tumor composed of atypical neoplastic, often pleomorphic cells that invade other tissues. "According to the list of the top 10 most frequently mutated genes, MUC4, MUC16, KMT2C, and PREX2 were annotated as cancer driver genes." (PMID 39338204, 2024). "There is a clear need for further mechanistic studies to explore the role of PREX2 and mutations of PREX2 in cancer." (PMID 28100393, 2017). "Furthermore, stringent analysis of combinations of databases revealed somatic mutations of PREX2 in an average of 3% of samples from different types of human cancers." (PMID 40365293, 2025). "The somatic mutation of PREX2 has been reported in several cancers." (PMID 30796242, 2019). "Questions remain concerning the role of PREX2 mutations in cancer." (PMID 28100393, 2017). "PREX2 may play oncogenic roles in human cancers through mutations." (PMID 30796242, 2019). "In terms of cancer-related genes, novel recurrent CNAs were identified in PREX2 (8q gain) and POLQ (3q gain) in the peritoneal fluid, plasma, and tissue." (PMID 35626111, 2022). "Taken together, we found that S1113R, a cancer-derived PREX2 mutant, significantly increased the proliferation and migration of HCC cells." (PMID 30796242, 2019). "Next, cell proliferation assays for these six cancer-derived PREX2 mutants were performed showing various effects on cell growth rates." (PMID 30796242, 2019). "PREX2 (also known as P-Rex2) was highly expressed in the brain, heart, skeletal muscle, placenta, and lymph node and promoted cancer cell migration and/or invasion." (PMID 30446011, 2018). "However, several small-molecule inhibitors that target the interface between PREX1/PREX2 and Rac, such as NSC23766 and PREX2-in 1, have been developed and shown preclinical efficacy in other cancers 44-46." (PMID 40365293, 2025). "It is possible that increased PREX2 expression contributes to a pro-tumorigenic environment in VS, similarly to that in other cancers, which may have secondary ototoxic effects that are unrelated to size alone." (PMID 37048724, 2023). "Notably, some identified 3′-UTR piSNV-affected genes, such as PREX2, ADAMTS12, and PLXDC2, were regarded as cancer-related genes with a high deleterious mutation rate." (PMID 35654793, 2022). "Thus, we inferred that PREX2, ADAMTS12, and PLXDC2 mutations lead to cancer development at both the protein function and posttranscriptional regulation levels." (PMID 35654793, 2022). "For example, PREX2 is an oncogene that interacts with PTEN gene product to inhibit PTEN phosphatase activity, thus activating the PI3K signaling pathway, which plays a role in insulin signaling pathways, and its mutations or overexpression have been observed in some cancers." (PMID 35654793, 2022). "Other studies have also shown that PTGDS, GREM1, LAMA4, S100A14, PREX2, and GLS2 have potential value in promoting cancer progression and predicting cancer prognosis." (PMID 37306872, 2023). "In terms of cancer-related genes, POLQ and PREX2 in the regions of gains and CASP8 and SF3B1 in the regions of loss were found in all samples, including the tissue, plasma, and peritoneal fluid." (PMID 35626111, 2022). "Seven top upregulated emRNAs and related to ccRCC or/and multiple malignant tumors, including CUL9, ATM, ARID1A, KMT2D, PBRM1, PREX2, and SETD2, were selected as candidate biomarkers for further testing." (PMID 36002886, 2022). "We identified 35 genes that were more frequently altered in HS/CB tumors versus corresponding TCGA cohorts; of which, 8 genes (PREX2, BIRC6, CNTNAP2, PTPRB, GRM3, ANKRD11, BRCA2, and TET3) are listed on the OncoKB Cancer Genes catalogue." (PMID 34446728, 2021).
cancer (continued). "However, PREX2 expression did not exhibit correlation with advanced TNM classification, cancer histologic grade, or position." (PMID 38609982, 2024).
adenocarcinoma (1 paper, 2023). A common cancer characterized by the presence of malignant glandular cells. "PREX2 mutations only occurred in males and smokers, and PREX2 mutations were significantly higher in patients with squamous than those with adenocarcinoma." (PMID 37301854, 2023).
PREX2 also shares sentences with these, for which no sentence is quoted: metastatic melanoma (3 papers); gastric cancer (2); glioblastoma (2); cholestasis (1); cutaneous melanoma (1); Depression (1); Duane syndrome (1); hearing loss (1); immune-deficiency (1); liver cirrhosis (1); melanoma in situ (1); metabolic disease (1); metabolic syndrome (1); stomach cancer (1); thyroid cancer (1).